RAB37 (RAB37, member RAS oncogene family)
Diseases named in the same sentence as RAB37 in open-access papers (continued):
Sharing a sentence is not in itself a finding about the gene and the disease.
cancer (continued). "We further investigated whether patients with intratumoral CD45+Rab37+IL-6+ expression profile correlated with cancer progression and poor prognosis." (PMID 34093869, 2021). "We have revealed a previously unrecognized anti-cancer stemness function of Rab37." (PMID 30158579, 2018). "It will be interesting to study whether additional cargos other than SFRP1 were involved in Rab37-mediated suppression of cancer stemness." (PMID 30158579, 2018). "In addition, Rab27A and Rab27B, the family members of Rab37, mediate exosomal pathways discarding tumor-suppressor microRNAs to enhance cancer progression." (PMID 30158579, 2018). "We previously identified Rab37 which shows tumor suppressor function by regulating exocytosis of thrombospondin-1 and tissue inhibitor of metalloproteinase 1 to the extracellular compartment, leading to inhibition of neo-angiogenesis and cancer metastasis." (PMID 30158579, 2018). "In addition, 5-Aza-2-deoxycytidine treatment of a highly metastatic lung cancer cell line shows demethylation and re-expression of the Rab37 gene and correlates with reduced cancer cell migration." (PMID 27716280, 2016). "Rab37 is another example of diverse functions in different types of cancers." (PMID 27716280, 2016). "Rab GTPases that regulate exocytosis (e.g., Rab27A and Rab37) could also be crucial for cancer progression." (PMID 25382899, 2014). "In addition, the ELISA results showed an increase of IFN-γ secretion upon anti-CD3/anti-CD28 stimulation (Left) and the lymphocyte-mediated cytotoxicity against cancer cell assay demonstrated an enhanced cancer cell killing effect of CD8+ T cells from Rab37 KO mice (Right)." (PMID 34093869, 2021). "In conclusion, our study provides a new mechanistic insight into the regulation of Rab37 activity by PKCα-dependent phosphorylation leading to inhibition of Rab37-mediated exocytosis of anti-migratory factor/cargo and thus facilitating cell motility and cancer metastasis." (PMID 29312551, 2017). "High tumor-infiltrating Rab37+ST2L+CD206+ signals correlated with advanced tumor stages and cancer recurrence." (PMID 38778059, 2024). "Multiplex fluorescence immunohistochemistry was performed to detect the protein level of Rab37 and CHI3L1, and localization of the tumor-infiltrating immune cells in allografts from mice or tumor specimens from cancer patients." (PMID 34987649, 2022). "Our biochemical and image analyses provide the first compelling evidence that Rab37 regulates SFRP1 for exocytosis to the extracellular compartment leading to inactivation of Wnt signaling and cancer stemness." (PMID 30158579, 2018). "Here, we report a previously uncharacterized mechanism by which Rab37 mediates exocytosis of secreted frizzled-related protein-1 (SFRP1), an extracellular antagonist of Wnt, to suppress Wnt signaling and cancer stemness in vitro and in vivo." (PMID 30158579, 2018). "Here, we report a novel anti-cancer stemness function of Rab37, which mediates secreted frizzled-related protein-1 (SFRP1), an extracellular antagonist of Wnt19–21, for exocytosis to suppress cancer stemness." (PMID 30158579, 2018). "IL-6 level was decreased in co-culture of A549 cancer cells and THP-1 macrophages with Rab37 knocked down, suggesting that Rab37-mediated IL-6 secretion in macrophage cells plays an important role in cross-talk between cancer cells, macrophages and T cells (Bar 7)." (PMID 34093869, 2021). "The last-mentioned two studies provide therapeutic strategies such as DNA demethylation of Rab37 gene and increased expression of Rab37 protein and its cargos such as TIMP1 could facilitate the development of anti-cancer treatment." (PMID 27716280, 2016). "The relationship between stromal Rab37 and IL-6 expression has never been examined in TME of human cancer patients." (PMID 34093869, 2021). "Moreover, the relationship between tumoral Rab37 expression and circulation CHI3L1 level has never been examined in human cancer patients." (PMID 34987649, 2022).
tumor (15 papers, 2013 to 2025). "Poor responders showed elevated IL-33 levels and increased infiltrating Rab37+ST2L+CD206+ tumor-associated M2 macrophages (yellow arrow)." (PMID 38778059, 2024). "These clinical results suggest that Rab37-mediated ST2 presentation is important in tumor-associated M2 macrophages during tumor progression." (PMID 38778059, 2024). "To exclude the physiological concern of Rab37 deficiency in mice, we firstly examined the serum biochemical parameters and histology of major organs from Rab37 KO and WT subcutaneous tumor-bearing mice." (PMID 38321486, 2024). "In view of the last-mentioned three studies, it is interesting to identify additional cargoes of Rab37 in tumor associated macrophages in TME." (PMID 35927755, 2022). "Patients with high proportion of CD45+Rab37+IL-6+ cells per region of interest (ROI) were significantly associated with advanced tumor stage (stages III and IV; P < 0.01)." (PMID 34093869, 2021). "A total of 39.4% (43/109) patients with low Rab37 expression were associated with advanced tumor stage (P = 0.039)." (PMID 30158579, 2018). "Furthermore, the correlation between Rab37+ST2L+CD206+ tumor-associated M2 macrophages was higher in advanced-stage patients." (PMID 38778059, 2024). "Interestingly, the tumour size in females was significantly smaller than in males, indicating a sex-associated regulation of RAB37 in tumour growth." (PMID 29229996, 2018). "The low level of Rab37 mRNA expression was associated with tumor metastasis." (PMID 29312551, 2017). "Clinically, the multiplex immunofluorescence-immunohistochemical assay indicated that patients with high Rab37+/PD-1+/TIM3+/CD8+ tumor infiltrating T cell profile correlated with advanced tumor stages and poor overall survival." (PMID 38321486, 2024). "The tumor weight and volume measurements showed that Rab37 KO CD8+ T cells suppressed the LLC tumor growth in the Rag1-deficient mice." (PMID 38321486, 2024). "In contrast, the expression of surface PD-1 in Rab37 KO tumor-infiltrating CD8 T cells was reduced compared to that in Rab37 WT tumor-infiltrating CD8 T cells." (PMID 38321486, 2024). "The results demonstrated that high Rab37 expression showed concordantly increased CHI3L1 level in the tumor infiltrated CD4+ T cells, CD8+ T cells and F4/80+ macrophages." (PMID 34987649, 2022). "Association study showed that plasma CHI3L1 levels correlated with tumor tissue Rab37 expression (P = 0.008), validating for the first time that Rab37 mediates CHI3L1 secretion in PDAC clinical model." (PMID 34987649, 2022). "Additional multiplex IF-IHC of CD163, CD8, PD-1 and panCK was performed on 20 tumor specimens, which were stained for Rab37, IL-6 and CD45." (PMID 34093869, 2021). "Clinically, NSCLC patients with increased intratumoral Rab37+IL-6+ immune cells where enriched with tumor infiltrated CD163+ M2-TAMs and exhausted PD-1+CD8+ T cells show poor prognosis." (PMID 34093869, 2021). "Here, we reveal novel findings that Rab37, a regulator of vesicle transport and protein trafficking, acts as a tumor promoter in stromal cells." (PMID 34093869, 2021). "We further examined physiological relevance of Rab37 KO in tumor metastasis using tail-vein injection model." (PMID 34093869, 2021). "IF-IHC demonstrated that co-expression of intracellular Rab37 and IL-6 with tumor-infiltrating CD45+ immune cells (CD45+Rab37+IL-6+) was observed especially in late stage patients." (PMID 34093869, 2021). "This study uncovers a novel function of Rab37 in suppressing tumor immunity and adds a new insight into the complexity of PD-1 regulation." (PMID 34093869, 2021). "Tumor-infiltrating CD8+ T cells derived from Rab37 KO mice showed reduced PD-1 expression compared to those from WT mice, indicating Rab37 involvement in PD-1 expression on CD8+ T cells." (PMID 34093869, 2021). "The results showed that LLC tumor growth in Rab37 KO mice was inhibited compared to that in WT mice." (PMID 34093869, 2021).
tumor (continued). "RAB37, as a tumor suppressor gene, promotes M1-like macrophage infiltration and suppresses tumor growth, and it was frequently down-regulated due to promoter hypermethylation in metastatic lung cancer, can serve as a potential predictive biomarker." (PMID 31169496, 2019). "The tumour samples from nude mice were then examined through immunoblotting with anti-LC3B and anti-RAB37 antibodies, which showed that LC3B-II levels decreased in RAB37 knocked-down tumours, whereas LC3B-II levels increased in RAB37-overexpressed tumours." (PMID 29229996, 2018). "RAB37-knockdown tumours showed tumour migration and an EMT phenomenon in both histological characteristics and EMT markers, indicating a regulatory role of RAB37 in tumour metastasis." (PMID 29229996, 2018). "Taken together, these results suggested that RAB37 promotes autophagy, thus at least partly prevents tumour metastasis." (PMID 29229996, 2018). "Histological and immunofluorescence analysis of tumour samples showed a denser cell growth in RAB37-knockdown than in RAB37-overexpressed tumours, a phenotype similar to the EMT phenotype." (PMID 29229996, 2018). "Further epithelial-mesenchymal transition (EMT) marker tests showed that β-catenin and N-cadherin were increased in RAB37-knockdown tumours, whereas it was decreased in RAB37-overexpressed tumours." (PMID 29229996, 2018). "Strikingly, patients with expression profile of low Rab37/low SFRP1/high Oct4 (Rab37−/SFRP1−/Oct4+) in their tumor specimens showed the worst OS and PFS." (PMID 30158579, 2018). "We further demonstrate that expression of Rab37 suppresses tumor progression by mediating exocytosis of TIMP1 and TSP1 to inactivate extracellular metalloproteinase 9 and to inhibit tumor neovasculature respectively." (PMID 29312551, 2017). "Therefore, MLTC was used to examine the proliferation of splenic CD4+ T cells derived from tumor-bearing Rab37 WT and KO mice by CFSE assay." (PMID 38321486, 2024). "Notably, T cell proliferation and activity were upregulated in tumor-infiltrating T cells from the tumor-bearing Rab37 knockout mice compared to those from wild type." (PMID 38321486, 2024). "Targeting PD-1, CTLA4, LAG3, or TIM3 axis may be a potential immunotherapy-based combination strategy to enhance population of cytotoxic effector T cells in patients with high level of Rab37+/PD-1+/TIM3+ tumor-infiltrating CD8+ T cells." (PMID 38321486, 2024). "It is worthy to investigate whether these Rab proteins and SNAREs could also be involved in Rab37-mediated PD-1 vesicle trafficking to the PM in tumor-specific T cells." (PMID 38321486, 2024). "Furthermore, the level of exhaustion markers (PD-1 and TIM3) was significantly diminished in Rab37 KO tumor-infiltrating CD8+ T cells compared to that in Rab37 WT tumor-infiltrating CD8+ T cells." (PMID 38321486, 2024). "Therefore, we performed tumor IHC with Rab37 and ELISA of plasma CHI3L1 from 103 PDAC patients whose tumor specimen and plasma samples were both available." (PMID 34987649, 2022). "The tumor infiltrating Rab37+CHI3L1+ cells were highly enriched with CD163+ M2 TAMs in the tumor sections from patients with advanced tumor stages, whereas early staged tumors displayed a low abundance of infiltrating Rab37+CHI3L1+CD163+ M2 TAMs and scattered intratumoral CHI3L1." (PMID 34987649, 2022). "Indeed, the anti-tumor effects of anti-PD-1 antibody (α-PD-1) therapy were abrogated in Rab37 KO mice." (PMID 34093869, 2021). "Notably, some tumours, when RAB37 knocked down, migrated to other body regions, such as the leg and the back, which indicated that RAB37 deprivation resulted in tumour metastasis." (PMID 29229996, 2018). "Importantly, addition of SFRP1 recombinant protein in Rab37 knockdown cells suppressed sphere formation in vitro and tumor initiation ability in vivo." (PMID 30158579, 2018). "RAB37 knockdown promoted tumour growth, whereas RAB37 overexpression inhibited tumour growth." (PMID 29229996, 2018).
tumor (continued). "Because autophagy suppression can promote tumorigenesis, an intriguing question is whether RAB37 is involved in tumour suppression by promoting autophagy." (PMID 29229996, 2018). "Rab37 has been postulated as a tumor suppressive small GTPase for trafficking anti-tumor cargos." (PMID 30158579, 2018). "RAB37 knockdown can decrease autophagy and increase tumour metastasis in vivo." (PMID 29229996, 2018). "RAB37 may exert its tumour suppression role through other processes, such as epigenetic modification, in addition to promoting autophagy." (PMID 29229996, 2018). "Moreover, Phospho-mimetic aspartate substitution mutant T172D of Rab37 significantly promotes tumor metastasis in vivo." (PMID 29312551, 2017). "In addition, the results of functional assay indicated an increase in cytokine production (TNF-α), proliferation (Ki67), cytotoxicity (CD107a), and activation marker (CD25) in tumor-infiltrating CD8+ T cells of Rab37 KO group compared to those in tumors of WT mice." (PMID 38321486, 2024). "To date, the role of Rab37 in tumor-infiltrating immune cells remains unknown." (PMID 34093869, 2021). "Therefore, we hypothesized that the patients with poor prognosis but preserved Rab37 expression may result from the dysfunction of Rab37 in their tumor tissues." (PMID 29312551, 2017). "The overall colocalization levels of Rab37, PD-1 and TIM3 were low in tumor-infiltrating CD8+ T cells in patients with better survival, whereas the colocalization levels of Rab37+/PD-1+/TIM3+/CD8+ T cells were increased in the patients with poor survival." (PMID 38321486, 2024). "In our study, upregulation of Rab37 in T cells by the TME results in sustainable PD-1 PM presentation accompanied with other co-inhibitory receptor TIM3 expression and reduced anti-tumor activity." (PMID 38321486, 2024). "We then observed for tumor growth of the subcutaneous syngeneic mouse LLC allograft model in WT and Rab37 KO mice." (PMID 34093869, 2021). "Our results suggest that Rab37/IL-6/PD-1 functions in the same axis and thus provide a rationale design using combined treatment of α-IL-6 and α-CTLA-4 to promote anti-tumor efficiency." (PMID 34093869, 2021). "Accordingly, patients with Rab37 low, SFRP1 low and Oct4 high expression profile correlates with progressive tumor stages and poor prognosis." (PMID 30158579, 2018). "Our results demonstrated that patients with concordantly decreased expression of both Rab37 and SFRP1 showed high expression of stemness marker Oct4 in their tumor specimens (P = 0.018)." (PMID 30158579, 2018). "These in vivo results further support the notion that Rab37 phosphorylation at T172 inactivates the Rab37-mediated TIMP1 secretion and thus promotes tumor metastases." (PMID 29312551, 2017). "The univariate Cox regression analysis revealed that patients with preserved Rab37, low TIMP1 and PKCα overexpression, with late stage, larger tumor size status, lymph node metastases or distant organs metastases had an increased risk for poor outcome." (PMID 29312551, 2017). "To validate the impact of Rab37-mediated PD-1 PM presentation on the functions of T cells in the TME, we performed subcutaneous tumor model in whole-body Rab37 KO and WT mice and then examined the functional signature of tumor-infiltrating T cells." (PMID 38321486, 2024). "Moreover, the results of IF-IHC assay indicated that the colocalization levels of Rab37, PD-1 and LAG3 were increased in tumor infiltrating CD8+ T cells in Rab37 WT group." (PMID 38321486, 2024). "However, tumor-infiltrating CD8+ T cells obviously reduced the expression of exhaustion markers (PD-1 and LAG3) in Rab37 KO tumors." (PMID 38321486, 2024). "Multiplex IF-IHC of Rab37, CHI3L1 and CD163 was performed on 23 tumor specimens." (PMID 34987649, 2022). "Therefore, we performed multiplex IF-IHC with Rab37, IL-6 and CD45 staining for tumor-infiltrating immune cells on tumor specimens from 62 NSCLC patients." (PMID 34093869, 2021).
tumor (continued). "Here, we reveal novel findings that Rab37 mediates CHI3L1 secretion in T cells and macrophages, the major constituent cells in TME, to promote M2 macrophage polarization and higher FOXP3+ Tregs to CD8+ T cells ratio in the tumor region, ultimately establishing an immunosuppressive TME." (PMID 34987649, 2022). "In addition, the anti-tumor effects of JAK2/3 inhibitor AG490 was observed in WT mice but not in Rab37 KO mice, consistent with the hypothesis of Rab37/IL-6/STAT3/PD-1 functioning in the same axis." (PMID 34093869, 2021). "Importantly, the relationship between Rab37 and CHI3L1 expression has never been examined in infiltrating immune cells in tumor tissue." (PMID 34987649, 2022).
infection (1 paper, 2020). The state of being infected such as from the introduction of a foreign agent such as serum, vaccine, antigenic substance or organism. "Several other Rabs displaying close phylogenetic relationship to Rab1, including Rab8, Rab18, Rab35, Rab33, Rab30, Rab19, and Rab37, could also be modified by SseK3 upon infection." (PMID 32504010, 2020).
RAB37 also shares sentences with these, for which no sentence is quoted: gastric cancer (2 papers); asthma (1); breast carcinoma (1); chronic lymphocytic leukemia (1); ciliopathies (1); colon cancer (1); colorectal cancer (1); esophageal SCC (1); hyperlipidemia (1); insulinoma (1); leiomyoma (1); lung squamous cell carcinoma (1); metastatic tumors (1); normal tension glaucoma (1); oral cancer (1); prostate adenocarcinoma (1); prostate transitional cell carcinomas (1); stomach adenocarcinoma (1).